SAMHD1 (SAM and HD domain containing deoxynucleoside triphosphate triphosphohydrolase 1)
Diseases named in the same sentence as SAMHD1 in open-access papers (continued):
Sharing a sentence is not in itself a finding about the gene and the disease.
tumor (continued). "Therefore, SAMHD1 is regarded as a tumor suppressor in certain tumors." (PMID 34480199, 2022). "Therefore, it was proposed that SAMHD1 might act as a tumor suppressor in neoplastic T-cells partly by apoptosis induction." (PMID 34480199, 2022). "It was described that the dNTPase function of SAMHD1 is important for this repair pathway as a balanced dNTP pool is necessary to avoid nucleotide insertions at repair junctions, potentially linking SAMHD1 dysfunction to genomic instability and thereby promoting tumor development." (PMID 34480199, 2022). "Therefore, we supposed that the combination of SAMHD1 silencing and radiotherapy might enhance the DNA damage and augment the anti-tumor immunity." (PMID 36578072, 2022). "The clinically approved drug pimitespib and IPI-504 also induced the depletion of SAMHD1 in HEK293T cells and in various tumor cell types (AGS, H9, HGC-27, and HeLa)." (PMID 41392286, 2025). "Therefore, reducing SAMHD1 expression in tumor cells may offer new antitumor strategies." (PMID 41392286, 2025). "Our in vitro data suggest that nuclear SAMHD1 slows the cell cycle by stalling mitosis, leading to reduced proliferation, and studies in HKO mice showed only modestly accelerated tumor progression post‐DEN induction." (PMID 39679869, 2025). "Our study identified a distinct pattern in SAMHD1 localization in HCC, with increased nuclear expression in tumor tissues compared to paratumor tissues, despite similar overall protein levels." (PMID 39679869, 2025). "Most importantly, the USP7 inhibitor sensitizes tumor cells to chemotherapy by decreasing SAMHD1, which implies the potential of targeting USP7-SAMHD1-CtIP axis to improve chemosensitivity." (PMID 37081042, 2023). "To further elucidate the regulation of USP7 on SAMHD1 protein stability, we next explored the effect of USP7-SAMHD1 axis on tumor cell survival under genotoxic insults." (PMID 37081042, 2023). "In conclusion, we here report a wide variability in SAMHD1 expression in MCL and a positive correlation to known biological adverse factors such as high tumor cell proliferation and blastoid/pleomorphic subtypes." (PMID 34738194, 2022). "Therefore, missing or mutated SAMHD1 might contribute to a pro-tumor microenvironment, as the cells are not able to correctly downregulate inflammatory signals like TNF-α in the absence of SAMHD1." (PMID 34480199, 2022). "SAMHD1 silencing synergized with radiotherapy to inhibit LUAD cell growth in vitro, so we examined the potential role of SAMHD1 in tumor growth in vivo." (PMID 36578072, 2022). "However, the role of SAMHD1 in anti-tumor immunity is still unknown." (PMID 36578072, 2022). "All five of the proteins predicted to be upregulated in EAC compared with normal esophagus (SAMHD1, ARHGDIB, AGR2, HSPA5, EPCAM) showed higher expression in the tumor sections compared with squamous epithelium." (PMID 28336725, 2017). "One significant scientific challenge is how to inhibit SAMHD1 function in tumor cells while preserving its function in normal primary cells." (PMID 41392286, 2025). "Together, these findings support SAMHD1's role as a modulator rather than an acute cell cycle checkpoint in tumor cells." (PMID 39679869, 2025). "SAMHD1 inhibits cGAS-STING pathway–mediated innate and adaptive immunity, and the absence of SAMHD1 reduces tumor-free survival." (PMID 40236649, 2025). "Similar to findings in clinical HCC samples, there was no significant change in SAMHD1 protein and mRNA levels in tumor tissues compared with liver lysates from vehicle‐treated control mice." (PMID 39679869, 2025). "Both SAMHD1 protein and mRNA levels showed no significant alteration in cancerous tissues compared to paired adjacent non‐tumor tissue." (PMID 39679869, 2025). "The depletion of SAMHD1 by HSP90 inhibitor, alongside the triggering of the cGAS-STING pathway, may not only contribute to tumor cell apoptosis but also enhance the anti-tumor effect of ara-C in AML cells." (PMID 41392286, 2025).
tumor (continued). "According to these results, we can conclude that SAMHD1 proteins in tumor cells, but not in multiple primary cell types, are vulnerable to HSP90 inhibition." (PMID 41392286, 2025). "Of note, cell viability of SAMHD1-overexpressed cells was significantly suppressed by DMXAA treatment, suggesting that STING activation could overcome SAMHD1-mediated tumor growth." (PMID 37781035, 2023). "We further demonstrate that de-ubiquitinating enzyme USP7 interacts with SAMHD1 and de-ubiquitinates it at lysine 421, thus stabilizing SAMHD1 protein expression for further interaction with CtIP for DDR, which promotes tumor cell survival under genotoxic stress." (PMID 37081042, 2023). "Finally, we observed a strong correlation between SAMHD1 expression and the activation of FAK and cortactin in tumor tissues obtained from patients with ccRCC." (PMID 37009792, 2023). "There is a rationale to pursue and further clarify the SAMHD1 expression and function because our observation in GBM tumor samples, patient-derived GBM cell lines, and established GBM cell lines strongly indicate that SAMHD1 expression status renders GBM more malignant and refractory." (PMID 36139652, 2022). "SAMHD1 was highly variably expressed in MCL (range, 0.4% to 100% of positive tumor cells)." (PMID 34738194, 2022). "The level of ARD1 was also elevated in tumor tissues as previously reported, implying that ARD1-mediated SAMHD1 acetylation levels may be upregulated in hepatocarcinoma." (PMID 28978134, 2017). "However, the data from the 12‐month timepoint highlight a distinct role for SAMHD1 in tumor progression rather than initiation." (PMID 39679869, 2025). "The tumor tissues had higher levels of SAMHD1 than non-tumor tissues, suggesting that SAMHD1 may be related to hepatocellular tumorigenesis." (PMID 28978134, 2017). "Furthermore, RNRi has potent monotherapy anticancer activity that would not be expected from direct SAMHD1 inhibitors, which is an important consideration when designing optimal combination therapies to tackle heterogeneity within both patient and tumour populations." (PMID 35583750, 2022).
neurological disorders (4 papers, 2014 to 2022). "If SAMHD1 can suppress HIV-1 replication at least moderately in microglial cells, artificial potentiation of SAMHD1 in microglial cells might be a novel approach to the treatment of HIV-1-associated neurological disorders." (PMID 24599229, 2014). "However, data from an animal model of HIV neurologic disorders may not be consistent with robust miRNA-mediated regulation of SAMHD1 in vivo." (PMID 26337901, 2015).
hematological cancers (3 papers, 2020 to 2024). "Additional evidence pointed towards a similar effect for other antiproliferative drugs used to treat hematological cancers as fludarabine, decitabine, vidarabine, and clofarabine, all considered substrates of SAMHD1, or forodesine an inhibitor of dGTP synthesis." (PMID 35158911, 2022). "SAMHD1, the unique dNTP triphosphohydrolase described in humans, has been proposed to play a key role in hematological cancers, although its value in advanced solid tumors has not yet been explored." (PMID 35158911, 2022).
hematological malignancies (3 papers, 2022 to 2024). "Apart from hematological malignancies, first studies on the role of SAMHD1 mutations in the development and progression of solid tumors were conducted only in recent years." (PMID 34480199, 2022). "Sterile alpha motif and histidine-aspartate (HD) domain–containing protein 1 (SAMHD1) is a deoxynucleoside triphosphate triphosphohydrolase with ara-CTPase activity that confers cytarabine (ara-C) resistance in several hematological malignancies." (PMID 38237141, 2024). "For example, targeting SAMHD1 by the Vpx protein has been found to benefit cytarabine therapy for hematological malignancies." (PMID 37081042, 2023).
vasculopathy (3 papers, 2020 to 2026). "Mutations in ACP5 and SAMHD1 are known to drive the pathogenesis of SPENCD and AGS, both of which are monogenic interferon diseases characterized by increased type I IFN signaling leading to vasculopathy, autoinflammation, and SLE-like disease." (PMID 35633950, 2022).
neoplastic disorders (1 paper, 2022). "The same is true for SAMHD1 with inflammatory, neurological and neoplastic disorders." (PMID 35633950, 2022).
SAMHD1 also shares sentences with these, for which no sentence is quoted: glioblastoma (4 papers); glaucoma (3); myeloma (3); non-small cell lung carcinoma (3); T-cell lymphoma (3); bacterial infection (2); brain disease (2); breast tumors (2); diffuse large B-cell lymphoma (2); genetic disorder (2); hereditary spastic paraparesis (2); infectious disease (2); sickle cell disease (2); acne (1); Aicardi Goutières syndrome 5 (1); Alagille syndrome (1); Alzheimer disease (1); aneurysmal disease (1); Arthritis (1); astrocytoma (1); atherosclerosis (1); atrial fibrillation and flutter (1); atrial septal defect (1); auto-inflammatory syndrome (1); autoimmune vasculitis (1); bladder cancer (1); bladder urothelial carcinoma (1); brain tumors (1); breast invasive carcinoma (1); calcinosis (1).
A further 62 diseases each share a sentence with SAMHD1 in 1 paper.